TATDN2 (TatD DNase domain containing 2)
Description:
Mg(2+)-dependent 3'RNA exonuclease and endonuclease that resolves R-loops via specific degradation of R-loop RNA structure. Shows no activity against D-loop and minimal activity against the RNA strand of an RNA-DNA hybrid duplex oligomer. Has no 3' or 5' exonuclease activity, no uracil glycosylase activity, and no 5' flap endonuclease activity on DNA substrates. May have a role in maintaining genomic stability through its role in R-loop resolution.
Synonyms: KIAA0218
Tractability: PROTAC: ubiquitination databases record sites on it; its protein half-life has been measured.
Gene: Protein-coding gene on chromosome 3 (10,248,023 to 10,281,218, forward strand). Ensembl gene ENSG00000157014.
Subcellular location: Nucleus
Subcellular location (Human Protein Atlas): Nuclear speckles
Pathways (Reactome):
Cellular responses to stimuli: XBP1(S) activates chaperone genes
Gene Ontology:
Molecular function: hydrolase activity, acting on ester bonds
Cellular component: nucleoplasm; nucleus
Genetic constraint (gnomAD): Loss-of-function variants: 44 observed, 62.16 expected, observed/expected ratio (o/e) 0.71, 90% interval 0.56 to 0.91. The upper end of that interval is the gene's LOEUF score, 0.91, which puts it in group 3 of 6, group 1 being the genes least tolerant of losing a copy. Missense variants: 997 observed, 987.92 expected, observed/expected ratio (o/e) 1.01, 90% interval 0.96 to 1.06. Synonymous variants: 399 observed, 374.21 expected, observed/expected ratio (o/e) 1.07, 90% interval 0.98 to 1.16.
Homologues: Orthologues: chimpanzee TATDN2 (99% identical), macaque TATDN2 (96% identical), pig TATDN2 (78% identical), dog TATDN2 (78% identical), mouse Tatdn2 (75% identical), rat Tatdn2 (74% identical), guinea pig TATDN2 (65% identical), tropical clawed frog TATDN2 (38% identical), zebrafish tatdn2 (31% identical), Caenorhabditis elegans Y37H2A.1 (18% identical), Caenorhabditis elegans Y24F12A.1 (17% identical). Paralogues in human: TATDN1 (9% identical), TATDN3 (8% identical).
Diseases named in the same sentence as TATDN2 in open-access papers:
TATDN2 is named in the same sentence as 16 diseases in open-access papers, as found by Europe PMC text mining. Sharing a sentence is not in itself a finding about the gene and the disease. The quoted sentences say what the papers report.
prostate carcinoma (3 papers, 2008 to 2025). A carcinoma that arises from epithelial cells of the prostate gland. "Dysregulation of TATDN2 is associated with a high rate of postoperative recurrence or subsequent metastases in cancers such as uveal melanoma, pancreatic cancer, prostate cancer, hepatocellular carcinoma, and head and neck squamous cell carcinoma." (PMID 41404808, 2025). "Five genes CGNL1, SUPV3L1, TATDN2, CASKIN1, and GOLGA7B are of unknown functions in either prostate cancer tumorigenesis or tumorigenesis in general." (PMID 30024105, 2018).
Nephropathy (1 paper, 2023). A nonspecific term referring to disease or damage of the kidneys. "Tag-SNPs captured by SLC17A3 rs942379 variant additionally impacts the expression of BTN3A2 in glomerulus and those captured by TATDN2 rs394558 variant combinedly affects the expression of ATP2B2 in glomerulus further elucidating its role in nephropathy related traits." (PMID 37696853, 2023).
pancreatic ductal adenocarcinoma (1 paper, 2025). An infiltrating adenocarcinoma that arises from the epithelial cells of the pancreas. "Human TATDN2 was identified as a substrate for ATM in response to radiation in pancreatic ductal adenocarcinoma by phosphoproteomic analysis." (PMID 41404808, 2025).
cancer (1 paper, 2025). A tumor composed of atypical neoplastic, often pleomorphic cells that invade other tissues. "Alterations in DDR proteins, including TATDN2, are associated with the development and metastasis of various cancers." (PMID 41404808, 2025). "On the other hand, recent research showed that TATDN2 is essential for the survival of BRCA1-deficient cancer cells but less so for BRCA1-repleted cancer cells." (PMID 41404808, 2025). "Recent research has identified human TATDN2 as a structure-specific RNase that participates in DNA repair under replication stress by resolving R-loops in BRCA1-deficient cancer cells." (PMID 41404808, 2025). "TATDN2 has recently been implicated in resolving R-loops and participating in the replication stress response in BRCA1-deficient cancer cells." (PMID 41404808, 2025). "Human TATDN2 functions as a structure-specific RNase to resolve R-loops and is required for the response to replication stress in BRCA1-deficient cancer cells." (PMID 41404808, 2025). "Meanwhile, human TATDN2 possesses RNA 3′ exonuclease and endonuclease activity to resolve R-loops and participates in response to replication stress in BRCA1-deficient cancer cells." (PMID 41404808, 2025). "Human TATDN2 has recently been found to function as a structure-specific RNase to resolve R-loops in vitro and be required for the response to replication stress in BRCA1-deficient cancer cells." (PMID 41404808, 2025). "Additionally, our study offers new insights into TATDN2’s complex pathologic roles in cancer biology." (PMID 41404808, 2025).
TATDN2 also shares sentences with these, for which no sentence is quoted: hepatocellular carcinoma (2 papers); asthma (1); Azoospermia (1); bladder cancer (1); head and neck squamous cell carcinoma (1); Infertility (1); pancreatic cancer (1); pheochromocytoma (1); retinal angiomas (1); tumor (1); type 1 diabetes (1); uveal melanoma (1).